Y_RNA (Y RNA )
Gene: Miscellaneous RNA gene on chromosome 5 (79,534,853 to 79,534,954, forward strand). Ensembl gene ENSG00000207391.
Homologues: Orthologues: chimpanzee Y_RNA (100% identical), macaque Y_RNA (86% identical). Paralogues in human: Y_RNA (89% identical), RNY3 (88% identical), Y_RNA (88% identical), Y_RNA (87% identical), Y_RNA (86% identical), RNY3P1 (85% identical), Y_RNA (85% identical), RNY3P14 (84% identical), Y_RNA (84% identical), RNY3P16 (83% identical), Y_RNA (83% identical), RNY3P4 (82% identical), and 96 more.